MIR340 (microRNA 340)
Synonyms: hsa-mir-340; MIRN340; mir-340
Gene: MicroRNA gene on chromosome 5 (180,015,303 to 180,015,397, reverse strand). Ensembl gene ENSG00000198995.
Gene Ontology:
Biological process: miRNA-mediated post-transcriptional gene silencing
Homologues: Orthologues: chimpanzee ptr-mir-340 (100% identical), macaque mml-mir-340 (99% identical), mouse Mir340 (99% identical), pig MIR340 (99% identical), guinea pig MIR340 (97% identical), rat Mir340-2 (97% identical), dog MIR340 (89% identical), rabbit MIR340 (65% identical).